ATP13A2 (ATPase cation transporting 13A2)
Diseases named in the same sentence as ATP13A2 in open-access papers (continued):
Sharing a sentence is not in itself a finding about the gene and the disease.
Kufor-Rakeb syndrome (continued). "Mutations in the ATP13A2 gene, belonging to the PARK9 PD susceptibility locus, lead to the Kufor-Rakeb syndrome (KRS), a severe early-onset autosomal recessive form of PD with dementia." (PMID 24904274, 2014). "Recessively inherited pathogenic mutations in ATP13A2 (ATPase type 13A2 gene) also result in impaired lysosomal proteolysis, leading to Kufor-Rakeb syndrome." (PMID 25061481, 2014). "Mutations in ATP13A2 have been associated with an autosomal recessive levodopa-responsive early-onset parkinsonism, known as Kufor–Rakeb syndrome (KRS, MIM# 606693)." (PMID 24399444, 2014). "Loss-of-function mutations in ATP13A2 (PARK9) are a known cause of Kufor-Rakeb syndrome (KRS), an autosomal recessive disorder characterized by juvenile-onset Parkinsonism associated with dementia." (PMID 24904274, 2014). "Recently, mutations in the human homolog of Ypk9, ATP13A2/PARK9, have been linked to Parkinson's disease (PD) and PD-like Kufor-Rakeb syndrome." (PMID 22457822, 2012). "A candidate gene in close vicinity to the highest peaks of the association analyses is the canine ATPase type 13A2 (ATP13A2) encoding a lysosomal type 5 ATPase in human known to be involved in Kufor-Rakeb-syndrome, a variant of Parkinson disease." (PMID 22022275, 2011). "For example, studies have demonstrated that Hnrnpa1 dysfunction contributes to neurodegeneration in multiple sclerosis experimental models, and mutations in ATP13A2 have been established as the causative factor for Kufor-Rakeb syndrome, a rare form of juvenile-onset Parkinsonism." (PMID 39858933, 2025). "ATP13A2 belongs to the diverse family of molecular pumps (P-type ATPases) and recessive mutations have been identified in patients affected by Kufor-Rakeb Syndrome (KRS), a juvenile form of familial Parkinson’s Disease (PD), which is characterized by cognitive impairment, myoclonus, and dementia." (PMID 36445873, 2022). "Mutations in ATP13A2 cause Kufor-Rakeb Syndrome (KRS), a juvenile form of Parkinson’s Disease (PD)." (PMID 36445873, 2022). "Mutations in lysosomal P5 type ATPase cation transporter, ATP13A2 (encoded by PARK9), which cause autosomal recessive parkinsonism (Kufor–Rakeb syndrome), produce severe mitochondrial fragmentation and mtDNA lesions in fibroblasts, potentially due to cellular zinc dyshomeostasis." (PMID 33372898, 2021). "In addition, mutations in the ATP13A2/PARK9 gene are thought to be strongly related to Kufor-Rakeb syndrome (KRS), an autosomal recessive kind of parkinsonian syndrome." (PMID 34576325, 2021). "In addition, mutations in ATP13A2 were associated with Kufor-Rakeb Syndrome (KRS), and neuronal ceroid lipofuscinosis (NCL)." (PMID 31289639, 2019). "We here expand the phenotypic spectrum associated with genetic variants in ATP13A2 that previously comprised Kufor-Rakeb syndrome, spastic paraplegia 78, and neuronal ceroid lipofuscinosis type 12 (CLN12), to also include juvenile-onset ALS, as supported by both genetic and functional data." (PMID 30992063, 2019). "To date, mutations in ATP13A2 have been associated with three overlapping yet distinct autosomal recessive disorders: Kufor-Rakeb syndrome (OMIM 606693), spastic paraplegia 78 (SPG78, OMIM 617225), and juvenile-onset neuronal ceroid lipofuscinoses (CLN12; 22388936)." (PMID 30992063, 2019). "Moreover, a set of genes related to atypical parkinsonian forms is known and includes ATP13A2, whose mutations cause the Kufor-Rakeb syndrome (PARK9)." (PMID 27637465, 2016). "Mutations in ATP13A2 lead to Kufor-Rakeb syndrome, a parkinsonism with dementia." (PMID 24904274, 2014). "Autosomal recessive loss-of-function mutations in the gene ATP13A2 (also designated PARK9) are causative for early onset Kufor-Rakeb syndrome, an autosomal recessive juvenile onset form of L-dopa-responsive parkinsonism that exhibits clinical features of Parkinson’s disease (PD)." (PMID 24252509, 2013).
Kufor-Rakeb syndrome (continued). "Biallelic pathogenic variants in ATP13A2, also known as PARK9, are associated with an autosomal recessive form of juvenile-onset parkinsonism, termed Kufor-Rakeb syndrome (KRS)." (PMID 39023817, 2024). "Biallelic mutations in the gene ATP13A2 cause Kufor-Rakeb Syndrome (KRS; OMIM#606693), also known as Parkinson’s disease-9 (PARK9), a juvenile form of Parkinson’s disease (PD)." (PMID 38249738, 2023). "Biallelic mutations in ATP13A2 have been found to cause a complex form of parkinsonism known as Kufor-Rakeb syndrome (KRS), characterized by juvenile onset parkinsonism, cognitive impairment, and a supranuclear gaze palsy." (PMID 35328025, 2022). "ATP13A2 is a transmembrane lysosomal P5-type ATPase, whose mutation results in the Kufor-Rakeb Syndrome, a form of AR-PD (PARK9)." (PMID 33297340, 2020). "PARK9 (encoded by ATP13A2) is a P-type ATPase of unknown function, but mutations in the ATP13A2 gene are associated with Kufor-Rakeb syndrome and are found also in patients with various other types of parkinsonism, causing an autosomal recessive parkinsonian syndrome." (PMID 33322668, 2020). "Loss of function mutations in ATP13A2 is the leading cause of Kufor-Rakeb syndrome (KRS), a rare form of early Parkinsonism." (PMID 31655107, 2020). "Mutations in ATP13A2 are associated with early-onset Parkinsonism, known as Kufor-Rakeb syndrome (KRS)." (PMID 30866990, 2019). "Mutations in ATP13A2 cause Kufor-Rakeb syndrome (KRS), a rare form of autosomal recessive juvenile-onset PD." (PMID 29616350, 2018). "Otherwise, mutations in ATP13A2 was reported to cause Kufor–Rakeb syndrome with juvenile onset and atypical clinical features including pyramidal signs, dystonia, cognitive decline, supranuclear gaze palsy and may become unresponsive to levodopa as the disease progresses." (PMID 29163333, 2017). "Notably mutations in ATP13A2 cause a parkinsonian-like syndrome, Kufor-Rakeb syndrome (KRS)." (PMID 25136353, 2014). "Since the first clinical discovery of the Kufor-Rakeb syndrome, numerous ATP13A2-related models have emerged, leading to significant advances in understanding the physiology and pathophysiology of this protein." (PMID 41935079, 2026). "Mutations in ATP13A2 (PARK9), an autophagy-related protein, cause Kufor–Rakeb syndrome, an autosomal recessive, juvenile-onset form of parkinsonism." (PMID 36675288, 2023). "Mutations in CLN12 (Park9), encoding the protein ATP13A2, result in juvenile-onset NCL in addition to Parkinson’s Disease type 9 (also referred to as Kufor-Rakeb syndrome)." (PMID 35159273, 2022). "Mutations in polyamine-transporting ATPase 13A2 (ATP13A2) cause a juvenile-onset form of NCL referred to as CLN12 disease, as well as Kufor Rakeb Syndrome, a juvenile-onset form of Parkinson’s disease." (PMID 35252181, 2022). "Lifetime risks between 0.04 and 0.07 per 100,000 in all datasets were found for Kufor-Rakeb syndrome (KRS; MIM ID # 606693) and aceruloplasminemia (ACP; MIM ID # 604290) based on pathogenic variants in ATP13A2 and CP, respectively." (PMID 35180557, 2022). "ATP13A2 (PARK9) is a lysosomal P-type ATPase and its loss-of-function mutation causes Kufor–Rakeb syndrome, a juvenile early onset parkinsonism." (PMID 33769432, 2021). "ATP13A2 (ATPase 13A2, MIM*610513) causes Kufor Rakeb syndrome (MIM#606693), an AR atypical JOPD with onset before 20 years." (PMID 34630269, 2021). "A recessive mutation in the ATP13A2 encoding for the lysosomal P-type ATPase “PARK9” causes the inherited parkinsonian syndromes ‘Parkinson's disease 9′ (or Kufor-Rakeb syndrome, PARK9, #606693)." (PMID 33362685, 2020). "ATP13A2 is directly responsible for Kufor-Rakeb syndrome, a rare juvenile form of PD, and participates in two other PD mechanisms: lysosomal iron storage and mitochondrial stress." (PMID 30564458, 2019).
Kufor-Rakeb syndrome (continued). "Mutations in the ATP13A2 (PARK9) gene, encoding a lysosomal ATPase, causes Kufor-Rakeb syndrome, a rare form of atypical, juvenile-onset autosomal recessive parkinsonism with pyramidal neurodegeneration and dementia." (PMID 31133790, 2019). "Novel mutations in ATP13A2 (ATPase type 13A2, PARK9, OMIM 610513) have been identified as a genetic cause of a rare juvenile-onset form of PD, named Kufor–Rakeb syndrome." (PMID 31083583, 2019). "Inactivation of ATP13A2, one of the four human P5B ATPases, leads to early-onset Parkinson’s disease (Kufor-Rakeb Syndrome)." (PMID 29547664, 2018). "The ATP13A2 (PARK9) gene is responsible for Kufor–Rakeb syndrome (KRS), a rare hereditary form of recessive, juvenile-onset, atypical parkinsonism with pyramidal tract signs and cognitive dysfunction." (PMID 30232368, 2018). "Parkinson disease 9 (PARK9 or Kufor-Rakeb syndrome, #606693) is a rare autosomal recessive juvenile-onset levodopa-responsive parkinsonism due to mutations in ATP13A2 (PARK9) encoding a lysosomal P-type ATP-ase." (PMID 29170650, 2017). "Such mutations in ATP13A2, also named PARK9, were first identified in 2006 in a Chilean family and are associated with a juvenile-onset, levodopa-responsive type of Parkinsonism called Kufor-Rakeb syndrome (KRS)." (PMID 25197640, 2014). "Mutations in ATP13A2 (PARK9), encoding a lysosomal P-type ATPase, are associated with both Kufor–Rakeb syndrome (KRS) and neuronal ceroid lipofuscinosis." (PMID 25565980, 2014). "First, loss-of-function of a neuronal lysosomal membrane protein P-type ATPase, ATP13A2, underlies an autosomal recessive form of early-onset Parkinsonism with pyramidal degeneration and dementia (PARK9, Kufor-Rakeb syndrome)." (PMID 20388210, 2010). "Overexpression of a ATP13A2 orthologue in yeast was shown to impart zinc resistance; on a different note, an individual with a mutant of ATP13A2 was affected with Kufor-Rakeb syndrome, a disease with shared features of Parkinsonism." (PMID 40708841, 2025). "Furthermore, mutations in ATP13A2 gene, also known as PARK9 have been associated with Kufor–Rakeb Syndrome, an early-onset variant of PD." (PMID 38918813, 2024). "In another familial form of PD (PARK9 or Kufor-Rakeb syndrome, #606693), caused by mutations in ATP13A2 (PARK9) encoding a lysosomal P-type ATPase, patients displayed typical eye movement abnormalities, including slow saccades with worse precision and increased latency of horizontal saccades." (PMID 37766983, 2023). "PARK9 encodes the transmembrane lysosomal P5-type ATPase ATP13A2, and missense or truncation mutations of PARK9 impair lysosomal function, resulting in autosomal recessive levodopa-responsive early-onset Parkinsonism, also known as Kufor-Rakeb syndrome." (PMID 34657636, 2021). "Mutations in ATP13A2 typically cause Kufor-Rakeb syndrome and also a late-onset autosomal recessive spastic paraplegia 78 (SPG78) and juvenile onset amyotrophic lateral sclerosis (ALS), whereas one family was diagnosed with CLN12 disease." (PMID 34733232, 2021). "Given the prior association of ATP13A2 with other motor neuron-affecting phenotypes like Kufor-Rakeb syndrome (MIM #606693), autosomal recessive spastic paraplegia type 78 (MIM #617225), and neuronal ceroid lipofuscinosis type 12 (CLN12; MIM #610513), this variant emerged as a strong candidate." (PMID 30992063, 2019). "Mutations in the ATP13A2 (PARK9) gene, encoding a lysosomal ATPase, cause a rare form of atypical, juvenile-onset autosomal recessive parkinsonism with pyramidal neurodegeneration and dementia - the Kufor-Rakeb syndrome." (PMID 28122627, 2017). "Mutations in the ATP13A2 gene (PARK9), encoding for a lysosomal type 5P-type ATPase, cause a hereditary rare juvenile onset autosomal recessive Parkinsonism with dementia named as Kufor-Rakeb syndrome." (PMID 26064418, 2015).
Kufor-Rakeb syndrome (continued). "Nevertheless, UCHL1 and FBXO7 interact with ParkinIP proteins, and therefore the RelatedPD subnetwork consists of a single connected component when ATP13A2, which is responsible for Kufor-Rakeb syndrome, a form of parkinsonism with dementia and juvenile disease onset, is excluded." (PMID 24244333, 2013). "Mutations in the ATP13A2 gene (PARK9) cause autosomal recessive, juvenile-onset Kufor-Rakeb syndrome (KRS), a neurodegenerative disease characterized by parkinsonism." (PMID 22768177, 2012). "The abnormal brain iron accumulation in the basal ganglia was also observed in other disorders, such as Kufor-Rakeb syndrome (KRS), Aceruloplasminemia (ACEP), Spastic paraplegia 35 (SPG35), and Jaberi-Elahi syndrome (JABELS), which were caused by mutated ATP13A2, CP, FA2H, GTPBP2, respectively." (PMID 38765101, 2024).
Parkinson disease (108 papers, 2010 to 2026). A progressive degenerative disorder of the central nervous system characterized by loss of dopamine producing neurons in the substantia nigra and the presence of Lewy bodies in the substantia nigra and locus coeruleus. "Conversely, ATP13A2 is genetically linked to early-onset parkinsonism and regulates lysosomal integrity, polyamine homeostasis, and neuronal resilience." (PMID 41751935, 2026). "Loss of the ATP13A2 gene (also known as PARK9) results in abnormal aggregation of α‐synuclein in Parkinson's disease." (PMID 40576306, 2025). "ATP13A2 is a lysosomal polyamine transporter with loss of function mutations linked to multiple neurodegenerative disorders including Parkinson’s disease (PD)." (PMID 40806164, 2025). "ATP13A2 (PARK9), a gene associated with a levodopa responsive form of parkinsonism, that is a member of the p-type ATPase transporter, involves α-syn externalization through exosomes." (PMID 38473923, 2024). "Loss-of-function mutations in ATP13A2 impair lysosomal acidification and are associated with early-onset parkinsonism." (PMID 37287072, 2023). "Mutations in the human ATP13A2, a lysosomal ATPase, is associated with pathogenesis of Parkinson’s disease." (PMID 37080960, 2023). "In a family with typical NCL pathology, mutation of the parkinsonism gene ATP13A2 was described as correlated with a JNCL form that the authors proposed should be termed CLN12." (PMID 37573956, 2023). "In previous studies of Parkinson's disease, ATP13A2 was always accompanied by a higher mutation rate; therefore, we subsequently explored the ATP13A2 mutation status in tumours." (PMID 37243374, 2023). "A previous study had reported that mutation of the human gene ATP13A2 causes Parkinsonism with dementia." (PMID 37577934, 2023). "Mutations in ATP13A2 gene, which encodes a lysosomal P5-type ATPase, leads to parkinsonism and impaired lysosomal acidification, thus decreasing lysosome mediated clearance of autophagosomes." (PMID 35874822, 2022). "Decreased expression of Atp13a2 is also associated with defective autophagy in midbrain dopaminergic neurons from a 1-methyl-4-phenyl-1,2,3,6-tetrahydropyridine-induced Parkinson’s disease mouse model." (PMID 35252181, 2022). "Pathogenic variants in α-syn (SNCA) gene have been also identified and associated to PD, while mutations in four genes (Parkin, DJ-1, PINK1 and ATP13A2) cause early-onset parkinsonism." (PMID 33210214, 2021). "Mutations in human ATP13A2 are associated with Kufor–Rakeb syndrome, an early onset form of Parkinson’s disease." (PMID 34946185, 2021). "Further atypical forms of parkinsonism, with juvenile onsets, include genes implicated in lysosomal function (ATP13A2) and synaptic vesicle endocytosis (SVE) pathway (DNAJC6 and SYNJ1)." (PMID 33381501, 2020). "We found that Parkinson’s disease-associated gene ATP13A2 promotes tumorigenesis through regulation of autophagy flux, which is responsible for the patient with PD was associated with lower risks of acquiring colon cancer." (PMID 33308286, 2020). "Mutations in the lysosomal transmembrane ATPase ATP13A2, the causal enzyme behind CLN12, have been linked to familial cases of Parkinson’s disease and juvenile-onset ALS." (PMID 32435656, 2020). "The gene responsible for this juvenile form of Parkinson has been identified as encoding the protein ATP13A2." (PMID 31319631, 2019). "The zinc transporter ZNT8 is a common autoantigen in type 1 diabetes, for example, and ATP13A2 (PARK9), a Parkinson’s disease gene, has been implicated in zinc homeostasis." (PMID 29223976, 2018). "The ATP13A2 gene (also known as PARK9) is mutated in autosomal recessive forms of early-onset Parkinsonism with pyramidal degeneration and dementia." (PMID 29063175, 2018). "Variants within genes associated with Parkinson’s disease (PARK9;ATP13A2), neuronal ceroid lipofuscinosis (NCL;TPP1) and hereditary neuropathy (DNMT1) were also identified." (PMID 27217339, 2016).